TNF (tumor necrosis factor)
Diseases named in the same sentence as TNF in open-access papers (continued):
Sharing a sentence is not in itself a finding about the gene and the disease.
tumor (continued). "Furthermore, CD4+ T cells have been shown to mediate direct cytotoxicity against tumor cells through increased production of interferon gamma (IFNγ) and tumor necrosis factor (TNFα in both preclinical models and patient-derived CD4+ T cells." (PMID 33383959, 2020). "Similarly, human U937 monocytic cells, which lack endogenous IgE bound on IgE Fc receptors prior to stimulation with anti-tumour IgE, also upregulated TNFα, MCP-1, and IL-10 expression with MOv18 IgE-dependent cytotoxic killing (ADCC) of tumour cells." (PMID 33203088, 2020). "During tumor progression, many angiogenic activators support the process of angiogenesis, such as vascular endothelial growth factors (VEGFs), interleukin 8 (IL-8), tumor necrosis factor α (TNF-α) and hypoxia-inducible factors (HIFs)." (PMID 31399389, 2020). "The results shown that plasma TNF-α increased significantly in the nude model mice, while C1 significantly reduced the increase in plasma TNF-α levels caused by tumor inoculation, and inflammation significantly improved the tumor microenvironment." (PMID 32015677, 2020). "Similar to those in initial GBMs, one of the GAM subpopulations (rM-1) could co-express anti-tumor (TNFα) and pro-tumor (IDO) markers, while PD-L1 was also highly expressed in the recurrent GAMs." (PMID 32457755, 2020). "An intriguing aspect of S100 proteins is that tumors induce the expression of S100 proteins by releasing VEGF-A, TGF-β, and TNF-α in metastatic target sites, mostly lung but also liver and kidneys, which serves as a chemo-attractant for metastasizing tumor cells." (PMID 32503348, 2020). "Higher levels of TNF-α in the saliva compared to serum may indicate cytokine activity directly in the tumor environment." (PMID 32855976, 2020). "In line with this, our findings of reduced TNF-α could potentially indicate accumulation in the GI tract tumour setting of DCs with altered maturational capacities." (PMID 32552799, 2020). "IL-33 enhanced the mRNA levels of pro-inflammatory factor TNFα, which might stimulate tumour proliferation and angiogenesis." (PMID 33308251, 2020). "It has also been reported that SMs themselves may have tumour-vasculature targeting properties, through the sensitisation of endothelial cells to TNF-mediated death." (PMID 31947615, 2020). "To more rigorously determine whether IFN-γ and TNF-α act directly on Tregs or via other cells present in the tumor microenvironment, we studied the effect of IFN-γ and TNF-α on purified Tregs in vitro." (PMID 32005826, 2020). "In addition, FWGE increases tumor necrosis factor α (TNFα) production by macrophages, leading to improved immune response towards tumor cells, inhibition of angiogenesis, and increased apoptosis of the target cells." (PMID 33456668, 2020). "Indeed, expression of IFN-γ and TNF-α was increased in tumor-infiltrating CD4+ and CD8+ T cells of Lsp1 KO mice, while it was markedly reduced in those of Lsp1 Tg mice." (PMID 33020243, 2020). "TNF-α is a potent pleiotropic pro-inflammatory cytokine produced by macrophages, neutrophils, fibroblasts, keratinocytes, NK cells, T and B lymphocytes, and tumor cells." (PMID 32784919, 2020). "Interestingly, TNF-α also controls gene expression of tumor cells as well as other components of the tumor microenvironment, such as fibroblasts, myofibroblasts, adipocytes and immune cells." (PMID 33202705, 2020). "TNF-α is known to exhibit anti-tumor activities in a variety of tumor cell lines." (PMID 32102503, 2020). "Additionally, it has been described that certain pro-inflammatory cytokines, such as tumor necrosis factor-alpha (TNF-α), can up-regulate PD-L1 expression in cancer cells, contributing to create an immunosuppressive tumor microenvironment." (PMID 32481540, 2020). "The loss of sensitivity of tumor cells to TNF could be mediated by TRAF2, given that inhibition of TRAF2 in tumor cells re-sensitizes them to TNF in vitro and improves the efficacy of ICB in mice bearing ICB-resistant tumors." (PMID 33344447, 2020).
tumor (continued). "Moreover, tumor-infiltrating CD8 T cells displayed diminished TNF-induced DNA damage, as measured by gH2AX." (PMID 32292509, 2020). "Another explanation might be that abnormal expression of IAPs and/or TNF by the tumor or stromal cells in its environment leads to addiction to NF-κB and/or TNFR1 signaling pathways." (PMID 32053868, 2020). "They demonstrated that inhibition of tumor acidosis by adenylyl cyclase inhibitor MDL-12 induces NOS, CXCL9, CXCL11 and TNF-α-expressing proinflammatory TAMs that phenotypically resemble classical M1 macrophages, leading to suppression of tumor growth in B16 mouse melanoma." (PMID 32707850, 2020). "TNFα belongs to a large family of cytokines playing roles in a plethora of processes, is commonly considered a tumor promoter, and is found to orchestrate both initiation and metastasization processes in animal models of CRC, also independently of inflammation." (PMID 32722560, 2020). "Besides, QRHX intervention can reduce the infiltration of TAMs in tumor tissues of lung cancer mice, reduce the expression of IL-6, TNF-α, ARG-1, CD31, and VEGF, and increase the expression of inducible NO synthase (iNOS)." (PMID 33224886, 2020). "Despite TNF anti‐tumor activity, its therapeutic use has been limited by high toxicity." (PMID 31916677, 2020). "Cytokines such as interleukins, interferons, or TNF-α function as molecular messengers, allow immune cells to communicate with one another, and are involved in tumor immune-surveillance in an efficiently regulated multifaceted, pleiotropic, and redundant manner." (PMID 32075247, 2020). "TNF-α is a potent inflammatory cytokine and tumour promotor, Bregs are known producers of TNF-α." (PMID 31901949, 2020). "Another study demonstrated that TNF-α increased EGFR expression in tumor cells." (PMID 32974124, 2020). "Reduction in the incidence of tumor lesions by naproxen may be due to its ability to increase TNF-a levels and decrease PGE2." (PMID 33489912, 2020). "We further evaluated the role of TNF/RIPK3 in the fate of KC post PH in tumor-inoculated mice." (PMID 33178579, 2020). "The levels of IL-6 and TNFα in tumor tissues were quantitated using ELISA." (PMID 32317968, 2020). "Additionally, previous research by Fischer and colleagues indicated a substantial role of eRNA in tumor cell migration through human cerebral microvascular ECs, including TNF-α secretion from tumor-infiltrating immune cells." (PMID 33015070, 2020). "In summary, the study shows that IL10 can inhibit the growth of transplanted tumor in vivo and the main mechanism may be the IL10-medited indirect inhibition of pro- inflammatory cytokines IL6 and TNF-α secretion and tumor angiogenesis." (PMID 32742480, 2020). "However, later studies found that in addition to killing tumor cells, TNF can function as an inflammatory mediator." (PMID 32993787, 2020). "Moreover, chronic levels of TNF-α and IL-6 in the TME have been linked to such phenomena as T cell exhaustion and facilitated tumor growth, respectively." (PMID 33154744, 2020). "We detected the levels of three key factors in the tumor group of mice: IL-1β, TNF-α and MMP9." (PMID 32796132, 2020). "In addition, the use of NF-κB or STAT3 inhibitor decreased PD-L1 expression in adi-CM-treated tumor cells, which provided more evidence that TNF-α and/or IL-6 signaling mediated the regulation of PD-L1 in adi-CM-treated tumor cells." (PMID 32477009, 2020). "Despite their overall tumor-promoting functions, certain subpopulations of TAMs can sustain antitumor activities including phagocytosis, antigen-presenting, or the release of proinflammatory cytokines such as TNF-α and IL-12." (PMID 32625204, 2020). "Moreover, TANs recruit several immunoregulatory cells which inhibit anti-tumor immunity and induce T cell apoptosis by releasing TNF-α." (PMID 33488669, 2020).
tumor (continued). "Phase 2 trials of recombinant TNF across a range of cancer types have so far not proven successful in causing tumour responses and associated with significant toxicity." (PMID 32805626, 2020). "TNFα is capable of inducing angiogenesis and tumor metastasis." (PMID 33214550, 2020). "We next investigated whether the combination of bevacizumab and anti-TNFα nanobody could inhibit the tumor epithelial–mesenchymal transition (EMT), which is an important indicator of tumor metastasis." (PMID 33214550, 2020). "In this context, sensitizing cells to TNF or other necroptotic stimuli by counteracting inducible NFκB or the protective functions of A20 may have potential therapeutic value to enhance anti‐tumor immunity." (PMID 33314666, 2020). "A more significant secretion of IFN-γ and TNF-α was found in the DCs cocultured with the supernatants from tumor cells infected with NDV-MIP3α compared with the supernatants of cells infected with NDV-WT, indicating a great benefit to the activation and differentiation of CD8+ and CD4+ T cells." (PMID 32759233, 2020). "Moreover, TNF-α can stimulate the vasoactive mediators such as interleukin and prostaglandin, and these mediators can promote the proliferation of tumor cells and significantly reduce the immune function." (PMID 32819324, 2020). "On the other hand, tumor-derived Programmed Death-Ligand 1 (PD-L1) engagement of its receptor, Programmed cell Death protein 1 (PD-1), expressed on CLs, decreased CL production of TNF." (PMID 32053868, 2020). "IL-17A+TNF+ TCRγδCD8− T cells might thus constitute a particularly detrimental cell population in the tumor and counteract the potential positive effect of Treg depletion on CD8αβ T cells." (PMID 32185408, 2020). "Ch/γ-PGA NCs were previously shown to significantly increase the production of IL-6 and TNF-α by macrophages and dendritic cells and to re-educate tumor macrophages towards a pro-inflammatory profile, decreasing the expression of CD163 and promoting the secretion of IL-12p40 and TNF-α." (PMID 32138314, 2020). "Adipose tissue secretes leptin, VEGF, IL-1, IL-6, hepatocyte growth factor (HGF) and TNF-α that could induce tumor neoangiogenesis leading to the progression of solid tumors." (PMID 32977765, 2020). "CAR macrophages could contribute to shifting the TME towards tumor rejection by releasing inflammatory cytokines such as TNF, IL-6, IFNγ, and IL-12, by promoting T cell recruitment and function, and tumor growth suppression." (PMID 32429316, 2020). "We noticed a significant therapeutic improvement when SM was combined with the current standard‐of‐care treatment (TNF/Mel), with TNF/Mel/SM being significantly more effective than TNF/Mel in shrinking tumour volume at the time of surgery (P ≤ 0.0001, unpaired t‐test with Welch's correction)." (PMID 32419365, 2020). "Conversely, TNF-α has also been observed to promote inflammation and tumor proliferation." (PMID 33292267, 2020). "Our previous studies showed that TNFα treated MSCs can express chemokines to recruit M2-like macrophages to promote tumor growth, suggesting these generally pro-inflammatory cytokines could induce immunosuppression through MSCs." (PMID 32509271, 2020). "Interestingly, NGR-coupled to the N-terminus of TNF has been reported to bind specifically to a CD13 isoform preferentially present in the tumor vascular cells." (PMID 32084238, 2020). "Furthermore, inflammatory cells produce large amounts of pro-tumorigenic cytokines, including tumor necrosis factor (TNF)-α and interleukin (IL)-6, which drive tumor progression." (PMID 32290483, 2020). "By specifically releasing IL-10 and TNF-α, TANs reduce the number of lymphocytes and even lead to their dysfunction, such that the outcome of this signaling is a suppressed immunologic reaction at the tumor site." (PMID 33022971, 2020). "IL-1β, TNF-α, and certain chemokines promote inflammation in non-tumor diseases." (PMID 32346605, 2020).
tumor (continued). "For instance, tumor necrosis factor (TNF)-related apoptosis-inducing ligand (TRAIL)-expressing EVs may potentially activate apoptosis in targeted tumor cells." (PMID 32610582, 2020). "Moreover, we further found that the expression of iNOS mRNA and TNF-α mRNA were decreased in tumor tissues, while CD206 mRNA and IL-10 mRNA were increased." (PMID 32595415, 2020). "Furthermore, HTiO2 nanoparticle-based SDT upregulated the levels of pro-inflammatory cytokines such as interleukin (IL)-1β, IL-6, and tumor necrosis factor (TNF)-α within the tumor, increasing the immune response against the tumor." (PMID 33505987, 2020). "M2-type macrophages and tumor cells are qualified to release TNF-α in a low concentration." (PMID 33505964, 2020). "The expression levels of IL-6 and TNFα were reduced in tumor tissues of mice treated with Trichomicin, which was consistent with results of in vitro experiments in which Trichomicin suppressed the expression of IL-6 and TNFα in tumor and stromal cells." (PMID 32317968, 2020). "Harnessing tumour-antigen specific CAR T cells as a vehicle to deliver TNF specifically to the tumour in combination with birinapant may have a significant therapeutic advantage." (PMID 31947615, 2020). "While it has long been known that TNF exerts its antitumor effect via stromal cells in the tumor microenvironment, we here demonstrated, using conditional TNF‐R1 reactivation knockout mice, that expression of TNF‐R1 on endothelial cells is sufficient for its antitumor effect." (PMID 31912630, 2020). "Interleukin-6 (IL-6), IL-10, and TNF are important triggers of myeloid origin inhibiting the proliferation and recruitment of MDSCs and are considered to be the main coordinator of immunosuppressive tumor microenvironment." (PMID 32547401, 2020). "Interestingly, production of IL12p40/p70 and TNFα by circulating cDC2s, and of IFNα and TNFα by tumor‐infiltrating pDCs were correlated together in patients." (PMID 33282290, 2020). "Adipose tissue is highly metabolically active and secretes pro-inflammatory cytokines such as interleukin (IL)-6 and tumor necrosis factor (TNF)-alpha which may promote tumor initiation." (PMID 33327948, 2020). "In addition, Trichomicin inhibited TNFα-induced activation of NF-κB and basal Stat3 signaling in vitro, which resulted in reduced expression of the immune checkpoint protein PD-L1 in tumor and stromal cells." (PMID 32317968, 2020). "Interestingly, this delivery system can lead to myeloid immune cell stimulation and subsequent release of cytokines, including TNFα and granulocyte macrophage-colony-stimulating factor (GM-CSF), with direct or indirect anti-tumor effects." (PMID 32668783, 2020). "Furthermore, administration of VSL#3 cocktail in AOM/DSS-treated mice significantly reduced the tumour load of animals, and decreased TNF-a and IL-6 in colonic tissue." (PMID 32575876, 2020). "Similarly, immunogenic cell death can involve TNF-α secretion via macrophages, which can lead to both tumor promotion as well as an antitumor activity, depending on the context." (PMID 33260534, 2020). "Moreover, tumor-infiltrating CD8+ effector T cells were more efficiently activated by VV-iPDL1/GM injections, as manifested by an enhanced expression of IFN-γ, TNF-α, and CD107a in response to the stimulation with tumor lysate-pulsed DCs." (PMID 32170083, 2020). "In this study, inflammatory cytokines that could enhance the tumourigenic process such as IL-6, IL-1β, and TNF-α were decreased in FLP-treated MO mice in the tumour tissues and serum compared to those of MO mice, which is in accordance with previous studies." (PMID 32308722, 2020). "In addition, metformin targets tumor-associated macrophages (TAM) by reducing TAM M1-like polarization thereby decreasing cytokine secretion of IL-1β, TNFα and IL-10 and affecting cancer outcomes such as reducing metastases." (PMID 32825010, 2020).
tumor (continued). "Sharing certain functional similarities with CypA in inflammatory process, CypB might also be responsible for RA cartilage erosion and chondrocyte-derived TNF-α is another regulator in mediating aberrant tumor-like behaviors of FLS." (PMID 32908452, 2020). "Furthermore, IL-6 and TNFα are highly expressed in the malignant tumor microenvironment, which can promote tumor invasion, distant tumor metastasis, angiogenesis, and tumor resistance." (PMID 32317968, 2020). "Finally, it should be mentioned that there is a third powerful strategy to locally release therapeutic amounts of TNF and IFNγ, which is the transfer of tumor antigen‐specific T cells that release the cytokines upon antigen encounter." (PMID 31916677, 2020). "Moreover, Hyp-PDT can reduce the cancer cell-secreted tumor-promoting cytokines, such as GM-CSF, IL-6, and TNF." (PMID 32340275, 2020). "TNF-α also enhances the inflammatory process in tumor development." (PMID 32455624, 2020). "Therefore, effects of hADSCs-IL2 on tumor growth would depend on the cumulative concentration of TNF-α secreted." (PMID 32560387, 2020). "Tumor cell necrosis as triggered by TNF activation of NF-κB was also accompanied with inflammation." (PMID 32117702, 2020). "Furthermore, OLFM4 has been shown to inhibit apoptosis-promoting factor GRIM-19 to induce anti-apoptosis and anti-apoptotic effects in tumor cells exposed to stress-inducing factors, such as hydrogen peroxide, tumor necrosis factor-α, and cytotoxic agents." (PMID 31923206, 2020). "In the tumor microenvironment, TNF-α is secreted by macrophages and tumor cells." (PMID 32149121, 2020). "Following these findings, which strongly point to TNF-α as a critical cytokine in early-macrophage induced tumor cell death, the question arises whether TNF-α inhibition can reverse the M0 induced cell death." (PMID 33267818, 2020). "Finally, muscles of wild type and Ager−/− mice were injected with TNFα/IFNγ or S100B in a tumour‐free environment." (PMID 32159297, 2020). "Macrophages are attracted to the tumor, and they produce TNF-α." (PMID 32310956, 2020). "Therefore, current immunotherapeutics need to be directed toward the induction of TNFα+ expression in TAMs, thereby reactivating anti-tumor immunity in the TME." (PMID 32219066, 2020). "In addition, higher TGF-β1, TSP-1, VEGF, and TNF-α levels are observed in 4T1 than in 67NR tumor tissue." (PMID 32156052, 2020). "TNF-α upregulates the emission of matrix metalloproteinase-9 (MMP-9) from tumor cells." (PMID 32194791, 2020). "According to the molecular context, TNFα exerts an opposite effect on tumor progression." (PMID 32219066, 2020). "Indeed, ELISA results indicated that the expression of serum TNFα, IL-12 and IL-6, which are functional markers of M1 macrophages, significantly increased in V&miR-99b-treated or V&miR-125a-treated tumor-bearing mice." (PMID 32948650, 2020). "TNF-α is a vital cytokine involved in inflammation and immunity, and could function as an endogenous tumor promoter." (PMID 32527042, 2020). "Also, it was shown that the presence of the HPV was associated with increased inflammatory cytokines (IL-1, IL-6, IL-17, TGF-β, TNF-α, and NF-kB) and tumor progression." (PMID 32458652, 2020). "At the single-cell level, surprisingly, the viSNE map showed that a certain GAM subgroup (M-1) could coexpress anti-tumor (TNFα) and pro-tumor (IDO) markers, while PD-L1 was also highly expressed in this subgroup." (PMID 32457755, 2020). "TNFAIP2 is a novel gene induced by TNF-α and can regulate inflammatory and tumor angiogenesis." (PMID 32793480, 2020). "More recently, S. boulardii administration to a mouse model of colitis-associated carcinogenesis induced by AOM/DSS was shown to reduce tumor incidence and size, to decrease colonic levels of the pro-inflammatory cytokines TNF-α and IL-6, and restore a balanced microbiota." (PMID 32523887, 2020). "Previous studies have showed that TNF-α can inhibit tumor angiogenesis." (PMID 32993787, 2020).